CD4 (CD4 molecule)
Diseases named in the same sentence as CD4 in open-access papers (continued):
Sharing a sentence is not in itself a finding about the gene and the disease.
Immunodeficiency (continued). "A declining CD4+/CD8+ ratio denotes a lack of resistance to infection such as HIV infection, immunodeficiency, and autoimmunity." (PMID 31015850, 2019). "The observation of significantly lower number of both CD4+ and FOXP3+ cells in the HIV‐only group compared with either of the HCV groups reflects both their immunodeficiency and absence of a hepatic pathogen." (PMID 24597693, 2014). "ICL diagnosis was confirmed by persistent CD4+ T lymphocytes count under 300cells/μL in the absence of HIV infection and common variable immunodeficiency." (PMID 22947084, 2012). "This is particularly important since IGRA based on the enzyme-linked immunospot (ELISPOT) technique appear not to lose sensitivity at lower CD4 counts although the impact of progressive HIV-related immunodeficiency on IGRA accuracy is still under study." (PMID 19236695, 2009). "Interestingly, the fact that most HIV-seropositive patients with malignant syphilis do not have a severely decreased CD4+ count may suggest that the pathogenesis of malignant syphilis is not related to a quantitative deficit in the immune system but rather to a qualitative immune dysfunction." (PMID 38541829, 2024). "We also did not observe any significant correlations between individual lymphocyte subsets or the CD4 + /CD8 + ratios and the seroconversion rate or achieved antibody titers — in the whole study group and the subgroups of children with and without immunodeficiency (p > 0.05)." (PMID 36149567, 2023). "The patient was without apparent immunodeficiency based on quantified results of white blood cell, lymphocyte, neutrophilic granulocyte, CD3+ T cell, CD4+ T cell, and CD8+ T cell counts and CD4/CD8 ratio, as well as total serum IgG, IgM, and IgA, which were in the normal range." (PMID 37404820, 2023). "The efficacy of COVID-19 vaccine for people with immunodeficiencies has not really been studied as, with the exception of people with well-controlled HIV infection (on therapy and with a CD4+ T‐cell count > 500), none of the registration trials included immunosuppressed subjects." (PMID 34178577, 2021). "However, we were unable to examine the relationship between hrHPV types and changes in immunodeficiency, because we did not have data on clinical correlates of HIV infection, such as CD4 cell count." (PMID 30125130, 2018). "Tissues from patients with CM but without HIV or other immunodeficiency show robust granulomatous inflammatory responses and CSF pleocytosis, whereas among those with HIV coinfection, CSF cell counts are lower and predominantly CD8+ rather than CD4+ T cells." (PMID 25492918, 2015). "Additionally, differences in CD4% and CD3%between survivors and nonsurvivors may reflect the severity of immune dysfunction and its impact on clinical outcomes." (PMID 40642098, 2025). "Also, in our study we did not evaluate other markers of immune dysfunction that are known to be important in HIV infection, such as immune activation, including increases in HLADR+ CD38+ CD4 and CD8 T cells, and immune exhaustion, characterized by increased expression of the marker PD1 on T cells." (PMID 33828220, 2021). "Even though ART treatment partially restored CD4 T cell frequencies in HIV+ women, the level of immune activation in cervical T cells remained high despite ART, indicating ART might not fully reverse HIV-induced immune dysfunction." (PMID 33007050, 2020). "However, with successful modern ART and viral suppression, absolute CD4 count and HIV viral load may not accurately reflect the risks facing patients because immune dysfunction persists despite normalization of CD4 counts." (PMID 29095912, 2017). "Thus, it is plausible that younger HIV patients have a more intact immune system that may not have such heightened sensitivity to CD4 T cell responses, consequently delaying their development of IRU until the occurrence of further immune dysfunction." (PMID 27822743, 2016).
Autoimmunity (1,105 papers, 2004 to 2026). The occurrence of an immune reaction against the organism's own cells or tissues. "Mechanistically, interferon-γ enhances β-cell PD-L1 expression in NOD islets, whereas loss of PD-1 on CD4+ T cells augment islet antigen–specific infiltration, underscoring the pathway’s role in restraining diabetogenic autoimmunity." (PMID 41607457, 2026). "Th9 cells are a CD4 T cell subset that produces interleukin-9 (IL-9), a pleiotropic cytokine implicated in allergies, autoimmunity and cancer." (PMID 41030439, 2025). "Collectively, this study reveals a novel mechanism underlying the functional bias of newly generated CD4+ T cells and the potential relevance of such a bias in autoimmunity." (PMID 40366856, 2025). "To understand the impact of OCA-B in T cell mediated autoimmunity, we used an Ocab conditional allele crossed to the CD4-Cre driver, which efficiently deletes OCA-B in T cells." (PMID 40299553, 2025). "To summarise, previously activated autoreactive CD4+T cells recognising citrullinated antigen:HLA complexes, linking citrulline autoimmunity to genetic risk, can be detected already in the risk phase." (PMID 40639878, 2025). "These variants result in reduced CTLA4 expression in CD4+ T cells, which impairs T-cell regulation and promotes autoimmunity." (PMID 41008338, 2025). "Alternatively, it is also possible that induction of CD4+ T cell tolerance is less stringent for inflammation-associated self-antigens, making them frequent targets in autoimmunity." (PMID 38992254, 2024). "The aberrant activation of ROCK2 in CD4+ T cells negatively affected its ability to phosphorylate, which suggested its potential to ameliorate pathogenic mechanisms in initiating autoimmunity." (PMID 38674328, 2024). "CXCR6+CD4+ T cells recently received much attention as prominent producers of cytokines and highly pathogenic effector cells during autoimmunity." (PMID 38838013, 2024). "Together, these results suggested that RNF213 deficiency in CD4+ T cells promoted autoimmunity by inhibiting immunosuppressive activity of Treg cells." (PMID 39013878, 2024). "On the other hand, deficiency of the m6A eraser ALKBH5 results in attenuated CD4+ T cell responses to repress autoimmunity due to increased m6A modification on IFNγ and CXCL2 mRNA." (PMID 37307819, 2024). "In this regard, DNA methylation dysregulation in CD4+ T cells has been linked to autoimmunity in patients with systemic lupus erythematosus (SLE)." (PMID 38186880, 2024). "Autoreactive CD4+ T cells are associated with autoimmunity, while cytotoxic CD8+ T cells play a role in fulminant myocarditis and antiviral defense." (PMID 37568452, 2023). "In this context, TGFβ signaling is crucial as TβRI deficiency in CD4 cells in mice results in the development of spontaneous autoimmunity in mice." (PMID 36855628, 2023). "TβRI or TβRII deficiency in CD4 cells results in the development of spontaneous autoimmunity in mice." (PMID 36855628, 2023). "Here, we reported that Neat1, which was upregulated significantly in CD4+ T cells, was an important regulator of pathogenic Th17 cell responses that contributed to the development of autoimmunity." (PMID 37716986, 2023). "This favors an inflammatory phenotype in intestinal CD4+ T cells and leads to migration to the CNS to cause autoimmunity." (PMID 37834203, 2023). "CD4+ Tcells initiate and control immunity to pathogens and cancer and areat least partly responsible for immunopathology associated with infection,autoimmunity, and allergy." (PMID 37554055, 2023). "Rab4a is known to regulate surface expression of CD4 via endosomal recycling and was shown to cause pro-inflammatory T cell lineage specification and to trigger autoimmunity." (PMID 35603192, 2022). "Naïve CD4+ T cells are activated to differentiate into Th17 cells, which cause autoimmunity and inflammation, and Treg cells, which inhibit autoimmune response and maintain immune homeostasis." (PMID 35705919, 2022).
Autoimmunity (continued). "Despite well‐established HLA class II associations in several autoimmune conditions, the disease‐driving antigen recognized by CD4+ T cells for most diseases remains elusive." (PMID 35119226, 2022). "Among the populations of CD8 cytotoxic T cells and CD4 helper T cells, regulatory T cells (Tregs) are a critical subpopulation of CD4+ T cells involved in preventing autoimmunity and having a greater association with GBM prognosis." (PMID 36338705, 2022). "Altogether these data support a pathogenic role of CD28+ CD27- TEMRA and EM CD4+ T cells in autoimmunity." (PMID 35185762, 2022). "Tregs, such as Foxp3-expressing CD4+ Treg cells, are central to preventing the loss of self-tolerance so that autoimmunity states can be induced." (PMID 36648885, 2022). "To determine if the effect was indeed specific to Th17 cells, we investigated the differentiation of naive CD4+ T cells into different T cell subsets strongly associated with autoimmunity in the presence of histones in vitro." (PMID 35082281, 2022). "T cell-mediated autoimmunity is also a key factor in RA occurrence and CD4+ T cells have been reported to be associated with the pathogenesis of RA." (PMID 35096114, 2022). "Although FAS is a natural regulatory checkpoint of T cells, it plays a role in autoimmunity and cancer, and activation-induced cell death is involved in loss of CD4+ and CD8+ cells in HIV patients." (PMID 33361110, 2021). "Androgen/androgen receptor complexes can directly induce anti-inflammatory IL-10 expression by CD4 + T cells, which has been proposed to underlie male protection from central nervous system (CNS) autoimmunity." (PMID 34930155, 2021). "Regarding patients with CGD, it is difficult to determine a clear role of CD4+ T cells in CGD-related autoimmunity risk." (PMID 33717180, 2021). "As a consequence, Peli1-deficient CD4+ T cells promoted lupus-like autoimmunity but protected against H1N1 influenza virus infection in mouse models." (PMID 33707688, 2021). "The autoimmunity in older adults is associated with the high levels of circulating T-regulatory cells (Treg) and reduced CD4/CD8 ratio." (PMID 34072224, 2021). "For instance, RASGRP1-dependent downregulation of DNA methyltransferase promotes CD4+ T cell hypomethylation, followed by induction of methylation-sensitive genes which are associated with autoimmunity." (PMID 31948396, 2020). "Our data thus far support a hematopoietic origin for the cellular mechanism by which Nod2 suppresses IRBP-induction of uveitis, which involves control over CD4+ T cells that cause organ-specific autoimmunity." (PMID 33106495, 2020). "When lymphopenia occurs, the CD4+ T-cells undergo homeostatic proliferation, which, when sustained, increases the risk for autoimmunity." (PMID 33361522, 2020). "IL-2 is required for the maintenance and survival of CD4 Tregs50,51 and IL-2 or receptor loss leads to reduced Tregs and autoimmunity onset." (PMID 33319815, 2020). "Adoptive transfer of Grail−/− CD4+ T-cells into lymphocyte deficient Rag1−/− mice aggravated experimental autoimmunity, indicating that the autoimmune phenotype of Grail−/− mice was predominantly driven by aberrant CD4+ T-cell responses." (PMID 32582770, 2020). "Common T-cell-dependent mechanisms of autoimmunity-associated CVD include CD4+CD28− expansion, CD8+CD28− expansion, Treg dysfunction, and proinflammatory cytokine production by T effector cells (Th1, Th17)." (PMID 33117403, 2020). "Tex have been reported in several immune models of infection, cancer, and autoimmunity with both CD4+ and CD8+ T cells susceptible to developing an exhausted phenotype as chronic TCR signaling is a hallmark of these conditions." (PMID 33603744, 2020). "Despite the success of the CD4+ T cell response, the breakdown of effective regulation can cause significant damage and autoimmunity." (PMID 33374787, 2020).
Autoimmunity (continued). "Her high peripheral blood T cells frequencies with increased HLA-DR and CD4/CD8 DP are probably linked with underlying autoimmunity such as IPF in our reported case or immunosenescence associated with ageing." (PMID 30709425, 2019). "Our review brings together studies from different areas of autoimmunity all of which suggest a role for CD28null CD4 T cells in causing or exacerbating disease." (PMID 30984377, 2019). "Treg cells were initially described as a CD4+CD25high T cell population whose depletion is associated with the development of severe multi-organ autoimmunity, and were defined by the expression of the transcription factor forkhead box P3 (FoxP3)." (PMID 31956323, 2019). "The highest genetic risk for autoimmunity is conferred by HLA class II genes, with odds ratios >6, suggesting that CD4 T cell responses are necessary for immunity against self." (PMID 31143179, 2019). "The documented role of CD161+ CD4+ T cells in pathogenic autoimmunity and their lineage connection to Th17 cells make them a possible candidate to serve as HIV-1 targets at the portal of entry." (PMID 31594817, 2019). "This last result shows that transferred alone CD4+Foxp3GFP− cells from healthy TCRminiAbEp mice to lymphopenic recipients expressing exclusively Ep or Ep63K analog caused autoimmunity." (PMID 31653839, 2019). "Trichloroethylene (TCE) is an industrial solvent and drinking water pollutant associated with CD4+ T cell-mediated autoimmunity." (PMID 31555266, 2019). "We propose that common selection by agonist self-peptides and limited intrathymic deletion enrich peripheral repertoire of CD4+Foxp3− cells in many dormant autoreactive clones that in suitable conditions can cause autoimmunity." (PMID 31653839, 2019). "While CD4+ T cells are primary cells in mediating adaptive immunity to a variety of pathogens, they are also a key player implicated in regulation of autoimmunity by their pro-inflammatory and pro-tolerance functions." (PMID 30327657, 2018). "In patients with CTLA4 deficiency the frequency of CD4+ Treg cells was normal or slightly decreased, suggesting that autoimmunity in these patients is caused by defective Treg function." (PMID 30443250, 2018). "The polarization of CD4+ T cells into distinct T helper cell lineages is essential for protective immunity against infection, but aberrant T cell polarization can cause autoimmunity." (PMID 28187197, 2017). "In both CTLA4-deficient and Foxp3-deficient mice, autoimmunity is driven by CD4 effector pathology, and depletion of Tregs in adult mice is associated with rapid onset of autoimmune pathology." (PMID 28646041, 2017). "We made use of a widely used model for peripheral autoimmunity wherein we transferred purified naive CD45RBhi CD4+ T cells from Itgax-Cre control mice into T cell–deficient Rag2−/− mice." (PMID 28130292, 2017). "Inhibiting T cell DNA methylation causes aberrant overexpression of genes that convert normal “helper” CD4+ T cells into autoreactive, inflammatory and cytotoxic cells that are sufficient to cause lupus-like autoimmunity in animal models." (PMID 28239687, 2016). "Th17 cells are a subset of CD4+ effector T cells that produce inteleukin-17 and are linked with tissue inflammation and autoimmunity." (PMID 28031822, 2016). "Th17 were first described as a CD4+ T-cell subset associated with chronic inflammatory processes, autoimmunity, allergy and transplant rejection." (PMID 26589145, 2015). "Our findings are important for designing vaccines against fungal infections in at risk individuals with CD4+ T cell defects and for immunotherapeutic intervention during infection and possibly autoimmune disorders." (PMID 26367276, 2015). "A better understanding of how memory CD4 T cells differ from their naïve counterparts will also inform on how best to control pathogenic CD4 T cells delivering new therapeutic approaches for antigen-specific tolerance in autoimmunity and allergy." (PMID 26441961, 2015).
Autoimmunity (continued). "In individuals predisposed to autoimmunity, it appears that effector CD4+ T cells resist cell death mechanisms, proliferate, and continue to produce inflammatory molecules that damage the host’s tissues." (PMID 25852682, 2015). "Ethnicity-specific inherited epigenetic susceptibility loci in CD4+ T cells provide clues to explain differences in the susceptibility to autoimmunity and possibly other T cell-related diseases between populations." (PMID 26609326, 2015). "Upon dendritic cell maturation, naïve CD4 T cells can differentiate into memory and Th1, Th2, and Th17 effector cells associated with autoimmunity." (PMID 24877157, 2014). "Because Tregs suppress CD4 driven autoimmunity, autoimmunity is a major cause of morbidity and mortality in these treatments." (PMID 24782861, 2014). "Even in the case of AIRE-deficiency, impaired tolerization of CD4+ T cells in the periphery by extra-thymic AIRE expressing cells likely contributes to the development of autoimmunity." (PMID 25182415, 2014). "Hg elicits higher cytokine production in LAG-3-deficient animals and adoptive transfer of wild-type CD4+ T cells can partially rescue LAG-3-deficient B6.SJL mice from Hg-induced autoimmunity." (PMID 25122007, 2014). "Collectively these results strongly argue that DM function is required for the development of CD4+ pathogenic effectors and demonstrate for the first time a causal relationship between DM-mediated peptide selection and autoimmunity." (PMID 23418596, 2013). "In humans, the presence of an autoimmunity-associated IL2RA haplotype correlates with reduced interleukin-2 responsiveness in stimulated CD4+ T cells and decreased ability of Tregs to suppress the proliferation of autologous effector T cells." (PMID 24154763, 2013). "CD4+NKG2D+ T cells have been reported to play a pathogenic role in autoimmune disorders such as Crohn’s disease or rheumatoid arthritis (RA) and their respective animal models." (PMID 24282598, 2013). "Multiple sclerosis (MS) is an autoimmune disorder characterized by demyelination, chronic inflammation, and neuronal damage primarily caused by activated, auto-reactive CD4+ and CD8+ T cells directed against myelin." (PMID 23787171, 2013). "One study found that a low count of absolute naive CD4+ T cells was associated with splenomegaly and autoimmunity." (PMID 22526591, 2012). "In combination with transforming growth factor-β, IL-6 is also involved in differentiation of naïve CD4+ T cells into a pro-inflammatory T helper (Th) 17 phenotype that has been associated with autoimmunity." (PMID 22509338, 2012). "IL17A and IL17F are mainly produced by a subset of CD4+ T cells (Th17 cells) and have been linked to a variety of inflammatory and autoimmune conditions." (PMID 22216338, 2011). "The recently discovered Th17 cells, a subtype of CD4+ T-helper cells mainly producing IL-17 and IL-22, have initially been linked to host defense against infections and to autoimmunity." (PMID 21197451, 2011). "In the STIM1 defect there is also CD4+ TReg lymphocyte deficiency, with severe autoimmunity (autoimmune thrombocytopenia, hemolytic anemia), enlarged lymph nodes and epatosplenomegaly." (PMID 21078154, 2010). "Additionally, for first time we show that TYK2:p.Pro1104Ala variant increases the regulatory CD4+ T cells, in line with the protective function of this variant in autoimmunity." (PMID 39835539, 2025). "Furthermore, our studies revealed a vulnerability in autocrine IL-21 CD4+ T cell signaling as a potential targeted approach to reduce ICI-associated autoimmunity." (PMID 40626363, 2025). "Moreover, we link the autoimmunity-associated polymorphism rs56258221 to dysregulation of CD4+ TN by shifting the balance of TH17 and TREG toward pro-inflammatory TH17 subsets." (PMID 38901430, 2024). "On the one hand, the depletion of CD4 + T cells by HIV could inhibit the development of CD4 + T cell-associated autoimmunity in untreated or late stage HIV patients." (PMID 38845026, 2024).